ALK (ALK receptor tyrosine kinase)
Diseases named in the same sentence as ALK in open-access papers (continued):
Sharing a sentence is not in itself a finding about the gene and the disease.
T-cell lymphoma (continued). "This subset of T-cell lymphoma often expresses anaplastic lymphoma kinase (ALK) in cases of ALK + ALCL and usually has a strong positivity for CD30." (PMID 26989539, 2016). "To examine the expression of Ik-1 and MZF1 proteins in formalin-fixed and paraffin-embedded ALK+ T-cell lymphoma tissues from patients, we initially attempted using immunohistochemical (IHC) staining." (PMID 25884514, 2015). "In T-cell lymphoma carrying the NPM-ALK fusion protein (ALK-TCL), miR-219 was found to target cell-stimulatory receptor ICOS (inducible T-cell co-stimulator or CD278) which was known to promote the proliferation of T-cells." (PMID 23690991, 2013). "As expected, ALK-positive ALCL showed a higher CR rate with anthracycline-based chemotherapy than other T-cell lymphomas." (PMID 22084700, 2011). "In addition, it explores emerging strategies for integrating ALK inhibitors into precision-based management of T-cell lymphomas, including combination approaches with chemotherapy, immunotherapy or antibody-drug conjugates." (PMID 41905770, 2026). "ALCL, ALK + is a common mature T-cell lymphoma and represents 15% of pediatric NHL." (PMID 39707053, 2025). "ALK- ALCL is the fourth most common T-Cell Lymphoma, representing 50% of sALCL cases." (PMID 40565334, 2025). "These pathways were previously associated with ALCL or T cell lymphoma subtypes and might be induced by increased ALK signaling in NPM::ALK Hdac1KO tumors." (PMID 40175628, 2025). "ALK-positive T-cell lymphomas generally exhibit better responses to chemotherapy and RT compared to ALK-negative variants, likely due to the oncogenic driver role of ALK mutations that render the cells more susceptible to targeted treatments, though no clear relationship with radiation is known." (PMID 40191738, 2024). "Furthermore, two different subtypes of T-cell lymphomas were found in our cohort: one ALCL CD30+/ALK+ and one PTCL." (PMID 37190220, 2023). "While ALK+ ALCL belongs to mature T cell lymphomas, loss of T cell identity is observed in the majority of ALCL secondary to a transcriptional and epigenetic repressive program induced by oncogenic NPM-ALK." (PMID 36698412, 2022). "Chimeric nucleophosmin (NPM)/anaplastic lymphoma kinase (ALK) is significantly associated with malignant cell transformation and NPM/ALK-carrying T cell lymphoma (ALK + TCL) cells abundantly express PD-L1, which is regulated by STAT3, and knocking down STAT3 can inhibit this effect." (PMID 35907881, 2022). "Activating mutations of STAT3 have been frequently detected in NK- and T-cell lymphomas including ALK-negative ALCL." (PMID 32922661, 2020). "However, as the clinical, histological, and genetic evidence mounted, a distinct entity of T cell lymphoma for the ALK-expressing subtype emerged." (PMID 29035291, 2017). "Thus, we resorted to using Western blotting to analyze the expression of Ik-1 and MZF1 in protein extracts from 15 ALK+ T-cell lymphoma patient tumor sections." (PMID 25884514, 2015). "Additionally, our data lend further support to the notion that ALK-fusion proteins confer high oncogenic potential to transformed cells of different origin independently of the fusion partner and induce both B- and T-cell lymphomas in transgenic mice." (PMID 21494621, 2011). "A study by the European T-Cell Lymphoma research group validated a three-gene model (TNFRSF8, BATF3, TMOD1) that was mostly expressed in ALK- ALCL, as revealed by RT-qPCR." (PMID 40565334, 2025). "Crucially, here the diagnosis was redirected towards a T-cell lymphoma via NGS testing, which identified a TRAF1::ALK translocation." (PMID 40161372, 2025). "Compared to the general population, the RSR for patients with ALK-positive ALCL was the highest, followed by those with EN NK/T-cell lymphoma." (PMID 40839148, 2025). "ALK gene rearrangements/fusions are commonly found in hematological malignancies such as ALCL, which is a moderately aggressive T-cell lymphoma." (PMID 37773318, 2023).
T-cell lymphoma (continued). "In T-cell lymphoma, the Nucleophosmin (NPM)/Anaplastic Lymphoma Kinase (ALK) fusion gene up-regulates PD-L1 via constitutive STAT3 activation." (PMID 36931099, 2023). "Among the T-cell NHL cases, one (ALCL CD30+/ALK+) had submandibular lymph node and diffuse abdominal involvement (spleen, small intestine, and mesenteric lymph nodes)." (PMID 37190220, 2023). "The PTCL subtypes were AITL (21/48, 43.8%), PTCL-NOS (12/48, 25%), NK/T-cell lymphoma (NKT, 7/48, 14.6%), and ALCL ALK+/- (4/48, 4/48, 8.3%)." (PMID 35747802, 2022). "In conclusion, we have demonstrated that BRG1 is expressed in a range of T-cell lymphomas and its protein levels are maintained by NPM-ALK activity in ALK+ ALCL cell lines." (PMID 35008316, 2021). "In this paper, we used two clinically utilized small molecule inhibitors, PPP and ASP3026, to antagonize the oncogenic kinases IGF-IR and ALK, respectively, in NPM-ALK+ T cell lymphoma." (PMID 31340850, 2019). "Approximately 80% of ALK+ T cell lymphoma cases harbor the nucleophosmin-ALK (NPM-ALK) oncogene, which results from the fusion of the ALK gene on the 2p23 chromosome to the NPM gene on the 5q35 chromosome." (PMID 31340850, 2019). "Although initial responses to selective ALK inhibitors are favorable, about 30% of the NPM-ALK+ T cell lymphoma cases develop resistance and have multiple relapses leading to disease-related morbidities and mortalities." (PMID 31340850, 2019). "Our results show that treatment of the NPM-ALK+ T cell lymphoma cell line DEL-R, which was resistant to the ALK inhibitor, with PPP induced downregulation of pIGF-IR and pNPM-ALK." (PMID 31340850, 2019). "In contrast, ALK+ALCL, a kind of T-cell lymphoma, typically involves the NPM1-ALK or TPM3-ALK fusion gene." (PMID 29747676, 2018). "The final cohort included 174 patients with PTCL-NOS, 144 angoimmunoblastic T-cell lymphoma (AITL), 74 ALK+ ALCL, 103 ALK-ALCL, 54 ENKL, 23 hepatosplenic T-cell lymphoma (HSTL), 16 EATL, and 12 subcutaneous panniculitis-like T-cell lymphoma (SPTL)." (PMID 29538376, 2018). "Noteworthy, the International T-cell lymphoma project has recently reported that ALK+ and ALK− ALCL seem to have a similar prognosis (in terms of both FFS and OS), when patients are stratified according to the clinical parameters (i.e., age and/or stage)." (PMID 21331150, 2010). "ALK-positive ALCL, although a T-cell lymphoma, should be considered in the differential diagnosis of ALK-DLBCL given its good prognosis." (PMID 19250532, 2009). "Primary cutaneous anaplastic CD30-positive (+) T-cell lymphoma is a rare variant of primary cutaneous lymphoma characterized by proliferation of large T lymphocytes with strong CD30 expression and no anaplastic lymphoma kinase (ALK) expression." (PMID 41970102, 2026). "ALCLs are considered CD30+ T cell lymphomas that can be broadly subcategorized as either ALK-positive or negative." (PMID 40166794, 2025). "Moreover, in T-cell lymphoma, the nucleophosmin (NPM)/anaplastic lymphoma kinase (ALK) fusion gene has been demonstrated to upregulate PD-L1 expression via constitutive STAT3 activation." (PMID 40075727, 2025). "As our understanding of the pathobiology of EBV+ mature T-cell lymphoma and ALK-negative ALCL advances, the classification of these two entities has been better defined." (PMID 38921179, 2024). "In enteropathy-associated T-cell lymphoma (types 1 and 2), primary cutaneous CD4 + small/medium T-cell lymphoma, peripheral T-cell lymphoma, NOS, and ALCL, ALK-negative, the error rates were 38.9, 75.0, 12.6, and 16.2%, respectively." (PMID 37046526, 2023). "Unlike many T-cell lymphomas, ALK+ ALCL can often be cured with the cyclophosphamide, doxorubicin, vincristine, and prednisone (CHOP) regimen." (PMID 37655119, 2023). "Anaplastic lymphoma kinase-negative anaplastic large cell lymphoma (ALK−ALCL) is a CD30-positive T cell non-Hodgkin’s lymphoma." (PMID 35406421, 2022).
T-cell lymphoma (continued). "It is a type of T cell lymphoma that presents similar morphological and immunophenotypic features to systemic ALK-negative ALCL." (PMID 35406421, 2022). "Further supporting our ALK- ALCL histology data, increased ROR2 expression was recurrently found in other independent ALK- ALCL patient samples and in a few other T cell lymphomas." (PMID 35246138, 2022). "For T-cell NHL, we only had two cases, at 7.62 (ALCL CD30+/ALK+) and 8.20 (PTCL) years." (PMID 36551614, 2022). "Additionally, our cohort has two different subtypes of T-cell lymphomas, i.e., one ALCL CD30+/ALK+ and one PTCL." (PMID 36551614, 2022). "BIA-ALCL is a rare primary non-Hodgkin T-cell lymphoma and it has been recently included within the group of anaplastic lymphoma kinase (ALK) negative ALCLs." (PMID 33131026, 2021). "Anaplastic large-cell lymphoma (ALCL) is a T cell Non-Hodgkin Lymphoma (NHL) which accounts for 10–15% of paediatric/adolescent cases, and which can be separated into two distinct subclasses based on differential expression of anaplastic lymphoma kinase (ALK)." (PMID 35008316, 2021). "Both RAC1 and CDC42 play a prominent role in the ALK-driven ALCL, a subtype of T-cell lymphoma." (PMID 31248017, 2019). "The human T cell lymphoma cell line Karpas 299 that carries the NPM (nucleophosmin)-ALK fusion gene was used as positive controls and these cells were strongly positive for total ALK and phospho-ALK (Tyr 1604)." (PMID 27009091, 2016). "Although the STAT3 signaling pathway has been reported to regulate PD-L1 expression in the NPM/ALK-carrying T cell lymphoma (ALK + TCL) cells, BM cell interaction did not activate STAT3 in B16F10 tumor cells." (PMID 25889536, 2015). "This case emphasizes a rare EBV association with a CD30 positive T-cell lymphoma where the morphologic and immunophenotypic findings are otherwise nondiscriminatory between PTCL, NOS and ALCL, ALK negative." (PMID 25143841, 2014). "Because of their selectivity and specificity to CD30 receptors, these aptamers were also used as agents to deliver siRNAs to Anaplastic lymphoma kinase (ALK) positive ALCL, which is an aggressive T-cell lymphoma that overexpresses ALK oncogenes and CD30 surface proteins." (PMID 25057429, 2013). "However, Brg1 is typically expressed in all cell types of adult tissue that undergo proliferation or self-renewal, so it is not necessarily surprising that human T-cell lymphomas (including ALK+ ALCL) express Brg1." (PMID 35008316, 2021). "We hereby report a unique case of CD30 positive T-cell lymphoma with anaplastic large cell morphology and diffusely strong Epstein-Barr encoded early RNA expression which highlights the diagnostic dilemma between ALCL, ALK negative and PTCL, NOS." (PMID 25143841, 2014). "This case emphasizes a peculiar CD30 positive immunophenotype with uniform Epstein-Barr encoded early RNA (EBER) expression in a subcutaneous T-cell lymphoma where the clinical presentation, morphology, and immunophenotype present a diagnostic dilemma between ALCL, ALK negative and PTCL, NOS." (PMID 25143841, 2014). "This entity is defined as a mature T-Cell Lymphoma with uniform, strong expression of CD30, without ALK expression or ALK rearrangements." (PMID 40565334, 2025). "The algorithm showed heterogeneous performance in T-cell lymphomas compared to B-cell lymphomas, except for ALCL and ALK-positive, which showed no error in presumptive diagnosis in all datasets (training, validation, and external validation)." (PMID 37046526, 2023). "PD-L1 expression has been found to be higher in a variety of T-cell lymphomas, including AITL, ATLL, ALCL (anaplastic lymphoma kinase [ALK]-positive and -negative), ENKTL, MF, Sézary syndrome and PTCL-not otherwise specified (PTCL-NOS)." (PMID 35681778, 2022). "BIA-ALCL is a rare T-cell lymphoma, CD30 positive, ALK-negative usually discovered after the diagnosis of spontaneous periprosthetic seroma or intracapsular mass around the breast implant." (PMID 34066230, 2021).
T-cell lymphoma (continued). "BIA-ALCL is an anaplastic lymphoma kinase (ALK)-negative and CD30-positive T cell lymphoma that arises in either the fluid or capsule surrounding the implant." (PMID 33185799, 2021). "Whereas ALK positive ALCLs are molecularly characterized and readily diagnosed, specific immunophenotypic or genetic features to define ALK negative ALCL are missing, and their distinction from other T-cell non-Hodgkin lymphomas (T-NHLs) can be controversial." (PMID 28061468, 2017). "A GEP analysis of T-cell non-Hodgkin's lymphoma samples, including angioimmunoblastic lymphomas (AILT), ALK positive ALCL, ALK negative ALCL, PTCL-NOS and normal T-cells, identified a genomic classifier for the recognition of ALCL patients." (PMID 28061468, 2017). "By analyzing SMARCB1 RNA and protein expression levels in multiple subtypes of mature T-cell lymphomas, we could exclude T-PLL, MEITL, EATL, MF, AITL and ALK-negative ALCL being the human counterpart of the phenotype observed in Smarcb1-deficient mice." (PMID 39362842, 2024). "Moreover, it was previously shown that the large majority of primary ALCL patient samples stained positive for IRF4 irrespective of ALK translocations, thus suggesting an important role for IRF4 in the pathogenesis of T-cell lymphomas." (PMID 29346274, 2018). "Among systemic T-cell NHL, 40 patients had a diagnosis of ALCL (ALK negative, N = 21 or ALK positive, N = 19), PTCL-NOS (N = 20), AITL (N = 9), T-cell lymphoblastic lymphoma (N = 3), enteropathy-associated T-cell lymphoma (N = 2), hepatosplenic T-cell lymphoma (N = 1)." (PMID 29515769, 2018). "A study from the European T-Cell Lymphoma Study Group identified a set of three genes (TNFRSF8, BATF3, and TMOD1) whose co-expression could potentially distinguish ALK-negative ALCL from PTCL-NOS, with an overall accuracy of approximately 97% in unrelated groups of patients." (PMID 38921179, 2024). "In addition, BIA-ALCL is a rare T-cell non-Hodgkin lymphoma that develops around a breast implant with a textured surface in both esthetic and reconstructive surgery, characterized as CD30-positive and anaplastic lymphoma kinase (ALK)-negative." (PMID 37374297, 2023).
breast carcinoma (149 papers, 2008 to 2025). "A patient with a past history of breast cancer who was diagnosed as having with ALK mutation-positive NSCLC, stage cT3N3M0." (PMID 31640606, 2019). "These recent studies have provided evidence for the emerging role of ALK as a potential molecular marker of diagnostic and therapeutic value in breast cancer." (PMID 26384210, 2015). "ALK overexpression is present in a substantial proportion of breast cancer cases and is significantly associated with aggressive tumor parameters." (PMID 26384210, 2015). "In view of the marked variation in results in ALK expression/mutation in breast cancer, questions arise whether ALK-targeted treatment strategies in breast carcinoma can be of benefit." (PMID 31393373, 2019). "In the process of PCD patterns affecting the prognosis of breast cancer, besides immune response, ALK, VEGFA/VEGFR2, NF-κB, HIF-1, PI3K-Akt, MAPK, and JAK-STAT signaling pathways played an important role." (PMID 40281780, 2025). "Separate validations were performed in 3,968 samples for ERBB2 amplification in breast cancer as a complement to the MI Cancer Seek tumor profiling validation, and in 9,213 samples for ALK fusions in NSCLC." (PMID 40804002, 2025). "In this report, we presented a case of heterochronous double primary malignancy involving breast cancer and ALK-positive advanced LCNEC." (PMID 39723252, 2024). "Here, we reported a case of heterochronous double primary malignancy of breast cancer combined with ALK-positive advanced LCNEC, in which the patient experienced a beneficial response to ALK-TKI therapy following the failure of postoperative adjuvant therapy." (PMID 39723252, 2024). "Within this group, only four recommendations were of tier 1 clinical evidence level (1x PIK3CA/KRAS-mutated breast cancer, 1x MET-mutated kidney cancer, 1x ALK fusion-positive NSCLC, and 1x BRCA2-mutated pancreas cancer)." (PMID 38136436, 2023). "Together, these data suggest that p-ALK is associated with resistance to PARP inhibitor/platinum therapy in ovarian and breast cancer." (PMID 36253486, 2022). "KLC1’s role in breast cancer, as a suppressor of epithelial-mesenchymal plasticity and translocation to the 5′ end of anaplastic lymphoma kinase (ALK), has been described previously." (PMID 36010968, 2022). "Clinical trials are currently ongoing that test the efficacy of entrectinib (a broad-spectrum kinase inhibitor for NTRKs, ROS, and ALK) in NTRK-rearranged solid tumors including breast cancer (NCT02568267, CT02097810)." (PMID 34650924, 2021). "In the last decades, a multitude of molecular abnormalities have been discovered representing potential druggable alterations, such as mutations of EGFR, ALK in NSCLC and HER2-mutations in breast cancer." (PMID 29881714, 2018). "EGFR mutation in non-small cell lung cancer (NSCLC), RET mutation in medullary thyroid carcinoma, ALK translocation and ROS1 translocation in NSCLC and HER2 amplification in breast cancer have been reported and therapies have been established." (PMID 30404198, 2018). "Alternative to binary scoring, an intensity-based quaternary scoring system (0–3+) was suggested for ALK IHC, similarly to HER2 (human epidermal growth factor receptor 2) diagnostic test in breast cancer." (PMID 30326973, 2018). "Using flow cytometry, we determined the membrane expression levels of all four HER-family members, IGF-1R, c-Met and ALK in our panel of breast cancer cell lines, with expression being represented as mean fluorescence intensity (MFI)." (PMID 28638122, 2017). "As such, in both incidence and amenability to ablative therapy, the percentage of patients with oligoprogressive metastatic estrogen receptor positive breast cancer appears significantly lower than that seen in ALK/EGFR positive NSCLC." (PMID 29147583, 2017). "The clinical and functional significance of chromosome 2 polysomy and extra copy numbers of ALK in breast cancer is yet to be elucidated." (PMID 26312204, 2015).